AGAP1 (ArfGAP with GTPase domain, ankyrin repeat and PH domain 1)
Description:
GTPase-activating protein for ARF1 and, to a lesser extent, ARF5. Directly and specifically regulates the adapter protein 3 (AP-3)- dependent trafficking of proteins in the endosomal-lysosomal system.
Synonyms: AGAP-1; Cnt-g2; GGAP1; CENTG2; KIAA1099
Tractability: PROTAC: ubiquitination databases record sites on it; its protein half-life has been measured.
Gene: Protein-coding gene on chromosome 2 (235,494,043 to 236,131,793, forward strand). Ensembl gene ENSG00000157985.
Subcellular location: Cytoplasm
Gene Ontology:
Molecular function: phospholipid binding; protein binding; GTPase activator activity; GTPase activity; GTP binding
Biological process: regulation of modification of postsynaptic structure
Cellular component: cytoplasm; postsynaptic endosome
Genetic constraint (gnomAD): Loss-of-function variants: 27 observed, 101.65 expected, observed/expected ratio (o/e) 0.27, 90% interval 0.19 to 0.37. The upper end of that interval is the gene's LOEUF score, 0.37, which puts it in group 1 of 6, group 1 being the genes least tolerant of losing a copy. Missense variants: 967 observed, 1,131.9 expected, observed/expected ratio (o/e) 0.85, 90% interval 0.81 to 0.9. Synonymous variants: 483 observed, 473.4 expected, observed/expected ratio (o/e) 1.02, 90% interval 0.95 to 1.1.
Homologues: Orthologues: guinea pig AGAP1 (98% identical), chimpanzee AGAP1 (95% identical), macaque AGAP1 (95% identical), dog AGAP1 (93% identical), pig AGAP1 (93% identical), rat Agap1 (93% identical), mouse Agap1 (91% identical), tropical clawed frog agap1 (86% identical), zebrafish agap1 (84% identical), rabbit AGAP1 (83% identical). Paralogues in human: AGAP3 (68% identical), AGAP2 (51% identical), AGAP5 (50% identical), AGAP4 (50% identical), AGAP6 (50% identical), AGAP9 (46% identical), ACAP3 (20% identical), ACAP2 (18% identical), ASAP1 (18% identical), ACAP1 (17% identical), ASAP2 (17% identical), ASAP3 (17% identical), and 16 more.
Diseases named in the same sentence as AGAP1 in open-access papers:
AGAP1 is named in the same sentence as 34 diseases in open-access papers, as found by Europe PMC text mining. Sharing a sentence is not in itself a finding about the gene and the disease. The quoted sentences say what the papers report.
autism (6 papers, 2006 to 2023). Persistent deficits in social interaction and communication and interaction as well as a markedly restricted repertoire of activity and interest as well as repetitive patterns of behavior. "Contrary to other studies where a haploinsufficiency of KIF1A, FARP2, HDLBP, and AGAP1 genes was cited as a possible cause for autism in 30–35% of 2q37DS, in our patients, autistic spectrum disorder was found in just one case." (PMID 36833393, 2023). "Even though a patient suffering from autism and intellectual disability was identified who has a genomic deletion encompassing SH3BP4 and AGAP1, it appears far more likely that loss of AGAP1 is the cause of the disease since this protein is known to play a role at synapses." (PMID 31671891, 2019).
autism spectrum disorder (3 papers, 2016 to 2023). A spectrum of developmental disorders that includes autism, and Asperger syndrome. "Heterozygous deletions and predicted damaging missense variants in AGAP1 are associated with a mixed neurodevelopmental phenotype that includes autism spectrum disorder and cerebral palsy." (PMID 37470098, 2023). "Missense variants in the Arf1 regulator gene AGAP1 and heterozygous deletions in the 2q37.2 region that span this gene are associated with autism spectrum disorder and cerebral palsy." (PMID 37470098, 2023). "In addition, AGAP1 is a candidate susceptibility gene for two neurodevelopmental disorders, autism spectrum disorder (ASD) and schizophrenia (SZ); yet its localization and function in neurons have not been described." (PMID 27713690, 2016).
breast carcinoma (3 papers, 2020 to 2022). "AGAP1 binds to FilGAP, a Rac-specific GTPase-activating protein, facilitating its targeting, and decreased AGAP1 expression is associated with promotion of cell migration in breast cancer cells." (PMID 33302475, 2020). "For example, the homologous protein AGAP1 mainly mediates the migration and invasion of breast cancer cells." (PMID 36100894, 2022).
osteosarcoma (3 papers, 2021 to 2024). A usually aggressive malignant bone-forming mesenchymal neoplasm, predominantly affecting adolescents and young adults. "While AGAP1 is found to be downregulated in osteosarcoma, its expression levels and function in prostate cancer have not been investigated." (PMID 38173042, 2024).
intellectual disabilities (2 papers, 2016 to 2019). "Moreover, here we demonstrate that deficiencies in AGAP1 generate dendritic spine deficits characteristic of developmental disorders associated with intellectual disabilities." (PMID 27713690, 2016).
asthma (1 paper, 2020). "The hypermethylated genes have roles in asthma (VGLL4, AGR2), neurologic development (AGAP1, OTX2), and immune regulation (SCAMP5, SLC11A1)." (PMID 32850550, 2020).
cerebral palsy (1 paper, 2023). A group of disorders affecting the development of movement and posture, often accompanied by disturbances of sensation, perception, cognition, and behavior. "Despite a statistical enrichment in AGAP1 variants in a cerebral palsy cohort, there is also evidence for environmental factors contributing to disease in several cerebral palsy patients with AGAP1 variants." (PMID 37470098, 2023). "We further identified 4/7 cerebral palsy patients with AGAP1 variants from previously published studies who also had an adverse event in their medical history." (PMID 37470098, 2023).
diabetes (1 paper, 2024). "The diabetes significant PFKFB3 SNP at the 10p15.1 locus (rs1983890) interacted with MAIP1 and AGAP1 collective SNPs in GGI analysis." (PMID 39313296, 2024).
Dystonia (1 paper, 2023). An abnormally increased muscular tone that causes fixed abnormal postures. "We noted movement disorders such as dystonia in patients with AGAP1 variants and previously showed locomotor impairments in CenG1a mutant flies." (PMID 37470098, 2023).
hepatocellular carcinoma (1 paper, 2023). A malignant tumor that arises from hepatocytes. "Furthermore, overexpression of Arf GAPs (i.e., AGAP1 and AGAP2) was identified in different cancer types such as breast, colon, lung, ovarian, and hepatocellular carcinoma." (PMID 37182141, 2023).
hypoplastic left heart syndrome (1 paper, 2024). Hypoplastic left heart syndrome (HLHS) refers to the abnormal development of the left-sided cardiac structures, resulting in obstruction to blood flow from the left ventricular outflow tract. "Down-regulation of AGAP1 (ArfGAP With GTPase Domain, Ankyrin Repeat, and PH Domain 1, 608651) in neo-hypoplastic left heart syndrome and up-regulation of such a gene in HF-hypoplastic left heart syndrome revealed the different effects of such gene during the pathogenesis of different CHD subtypes." (PMID 39202774, 2024).
Immunodeficiency (1 paper, 2023). Failure of the immune system to protect the body adequately from infection, due to the absence or insufficiency of some component process or substance. "Consistent with the report on one patient with an AGAP1 variant, the patient with the AP3D1 variant had immunodeficiency and died of septic pneumonia at the age of 3.5 years." (PMID 37470098, 2023).
leukaemia (1 paper, 2023). "Previous studies have reported that AGAP1 was highly expressed in IGH::DUX4 types of leukaemia." (PMID 38115701, 2023).
microcephaly (1 paper, 2023). A congenital or acquired developmental disorder in which the circumference of the head is smaller than normal for the person's age and sex. "Patients with AGAP1 variants also exhibited microcephaly, impaired cortical growth and delayed myelination, and AGAP1 is known to be important for dendritic spine maturation." (PMID 37470098, 2023). "This suggests that the synaptic size phenotype is AGAP1 dependent, but with haploinsufficient inheritance of microcephaly in humans and recessive inheritance of NMJ size defects in the fly." (PMID 37470098, 2023).
myeloma (1 paper, 2015). "It is also noteworthy that the 37 top deregulated genes were enriched for the myeloma “stem cell” gene set, including NUDT11, PKP2, ROBO1, AGAP1, NAP1L3 and EPDR1, indicating that “stemness” may play an important role in determining high risk behavior." (PMID 24913504, 2015). "Notably, six of the top deregulated genes (NUDT11, PKP2, ROBO1, AGAP1, NAP1L3 and EPDR1) were recently identified as “stem cell” genes in myeloma." (PMID 24913504, 2015).
ovarian carcinoma (1 paper, 2023). A malignant neoplasm originating from the surface ovarian epithelium. "Together, these data indicate that AGAP1 is required for invasion in Pten‐null cells and that ovarian cancer patients with high ARF6 and AGAP1 levels, irrespective of the isoform of the AGAP1, have a poor clinical outlook." (PMID 37577760, 2023).
neurodevelopmental disorder (5 papers, 2016 to 2025). A behavioral and cognitive disorder with onset during the developmental period that involves impaired or aberrant development of intellectual, motor, or social functions. "The shared clinical features of this expanded cohort provide additional support that AGAP1 variants can lead to a mixed neurodevelopmental disorder with systemic manifestations." (PMID 37470098, 2023). "PTPRN2, MAD1L1, and AGAP1 are all linked to neurodevelopmental disorders and associate significantly with PAE or FASD in two or more previous genome-wide DNAm studies." (PMID 36581877, 2022). "Hypermethylation of Agap1 is associated with neurodevelopmental disorders through interference with the cellular structure and internal functioning of neurons and through interactions with other genes, particularly the Dtnbp1 gene." (PMID 35893036, 2022). "Diverse evidence suggests that AGAP1, AP-3, and BLOC-1 subunits are risk factors in neurodevelopmental disorders." (PMID 27713690, 2016). "Our data argue that AGAP1 phenotypes are not a general feature downstream of genetic defects associated to neurodevelopmental disorders." (PMID 27713690, 2016). "Although this will require additional experimental validation, we suspect that this phenomenon may be broadly applicable to a variety of gene–environment interactions that contribute to human neurodevelopmental disorders and is not unique to AGAP1 variants." (PMID 37470098, 2023). "However, AGAP1 localization, function, and susceptibility to mutations in genes associated with neurodevelopmental disorders have not been explored in neurons." (PMID 27713690, 2016). "Collectively, these data indicate that fine-tuned expression of AGAP1 is necessary the formation and maturation of dendritic spines during brain development, suggesting that AGAP-dependent mechanisms play a role in the pathogenesis of neurodevelopmental disorders." (PMID 27713690, 2016).
neurological disorders (3 papers, 2020 to 2024). "Hypermethylated genes involved in neurological disorders include AGAP1, CACNA1A, and OTX2." (PMID 32850550, 2020). "Two other genes, AGAP1 and MEGF9, with QVs in six patients each, currently lack nervous system-related information in OMIM, Reactome, and GO, but recent articles have provided additional insight into the role of AGAP1 and MEGF9 in nervous system disorders." (PMID 39329968, 2024).
cancer (2 papers, 2020 to 2023). A tumor composed of atypical neoplastic, often pleomorphic cells that invade other tissues. "Therefore, phenanthriplatin may act to modulate the cytoskeleton and cancer invasion through distinct pathways from those used by cisplatin, including a pathway incorporating AGAP1 and FilGAP signaling, while cisplatin signaling may not integrate this mechanism." (PMID 33302475, 2020). "We also found that phenanthriplatin, but not cisplatin, downregulates two genes, AGAP1 (ArfGAP with GTPase domain, ankyrin repeat and PH domain 1) and DIAPH2 (diaphanous related formin 2), involved in cancer cell cytoskeletal remodeling." (PMID 33302475, 2020).
infection (2 papers, 2022 to 2025). The state of being infected such as from the introduction of a foreign agent such as serum, vaccine, antigenic substance or organism. "It is of note that there were six proteins (Chm, Tgm3, Arhgap24, Tanc1, Agap1, Pnkd) that were uniquely expressed on the third day after infection." (PMID 36061859, 2022).
tumor (2 papers, 2023). "In five of seven bulk tumour data sets, AGAP1 mRNA expression was elevated in tumour compared with normal ovarian tissue, which occurred in the epithelium in independent LCM tumour data sets, but not consistently in the stroma." (PMID 37577760, 2023). "Both the CYTH2 GEF and AGAP1 GAP mRNAs were elevated in tumour tissue in a number of data sets; however, CYTH2 contribution is complicated by poor outcome being specifically conferred by the PIP3‐associating CYTH22G isoform." (PMID 37577760, 2023).
AGAP1 also shares sentences with these, for which no sentence is quoted: developmental delay (2 papers); schizophrenia (2); behavioral disorders (1); brachydactyly (1); epilepsy (1); gastric cancer (1); glioma (1); hemifacial microsomia (1); movement disorder (1); Oligodontia (1); prostate carcinoma (1); retinal degeneration (1); sleep disorder (1).